ENSG00000300552 (novel transcript)
Gene: Long non-coding RNA gene on chromosome 8 (33,513,466 to 33,513,589, forward strand). Ensembl gene ENSG00000300552.
Gene Ontology:
Biological process: RNA processing
Cellular component: nucleolus